APP (amyloid beta precursor protein)
Diseases named in the same sentence as APP in open-access papers (continued):
Sharing a sentence is not in itself a finding about the gene and the disease.
neurodegenerative disease (continued). "Further, HuD regulates the expression of mRNAs involved in the pathogenesis of neurodegenerative diseases or cancer, including amyloid precursor protein (APP), β–site APP–cleaving enzyme 1 (BACE1), lncRNA BACE1AS, neprilysin (NEP), tau, superoxide dismutase 1 (SOD1), and MYCN." (PMID 33922479, 2021). "Our study provides novel information regarding the influence of genetics and the impact of DIO on APP gene expression in the olfactory bulb, which may be connected to neurodegenerative disease." (PMID 33371327, 2020). "A deep understanding of APP function in maintaining vascular homeostasis might shed light on new therapeutic targets and provide a new perspective on treatment options of neurodegenerative diseases." (PMID 33228083, 2020). "Understanding the influence of APP roles on the functionality of the vascular system might shed light on new therapeutic targets and provide a new perspective on treatment options of neurodegenerative diseases." (PMID 32973564, 2020). "Based on this evidence, the alteration of APP expression and processing affects the integrity and functionality of neurovascular tissues, and this may be a critical step in the pathogenesis of neurodegenerative diseases." (PMID 32973564, 2020). "The ability of Xn to modulate multiple proteins, pathways and functions to effect reduction of AD-like pathology expressed by N2a/APP cells might have advantages in treating this complex neurodegenerative disease." (PMID 29670521, 2018). "The presence of genes for neurodegenerative diseases that have human orthologs, such as amyloid precursor protein (APP), tau, and UNC13A, as well as the wide array of transgenic strains, constitute the formidable advantage of using C. elegans to study neurodegeneration." (PMID 29563862, 2018). "Therefore, the identification of small molecular IRE chemical inhibitors to reduce APP and α-Syn levels and alleviate protein aggregation can have therapeutic significance to human neurodegenerative diseases." (PMID 29061112, 2017). "Therefore, inhibition of the IRE-modulated expression of APP and α-Syn or chelation of iron in patient’s brains has therapeutic significance to human neurodegenerative diseases." (PMID 29061112, 2017). "Lastly, neurotoxic and neuroprotective APP fragments may trigger or alleviate pathophysiological mechanisms involved in neurodegenerative diseases." (PMID 28539872, 2017). "The immunomodulatory effect of BS-I in APP/PS1 mice indicates the therapeutic potential of this drug for AD, because neuro-inflammation is a critical risk factor for neurodegenerative disease, and the modulation of the immune system is widely accepted to be able to influence disease progression." (PMID 26946062, 2016). "Finally, to assess the involvement of IL-19 in neurodegenerative diseases, we investigated the expression pattern of IL-19 in a mouse model of AD using APP/PS1 Tg mice." (PMID 25794104, 2015). "Unravelling how APP is embedded into individual networks within neurotransmitter release sites and how disturbances of the network may account for neurodegenerative diseases needs to be addressed in future studies." (PMID 26834621, 2015). "Overexpression of S100B in the mice brain is known to accelerate neurodegenerative disease pathology, including AD and PD, and promote the synthesis of APP mRNA and APP in neurons, which could serve as a source of additional Aβ accumulation." (PMID 24586443, 2014). "AD is a non-curable neurodegenerative disease with the majority of cases (85–90%) being sporadic and just 10–15% familial and caused by mutations in key genes such as Amyloid Precursor Protein (APP), Presenilin 1 (PSEN1), and Presenilin 2 (PSEN2), involved in the metabolic pathway of APP." (PMID 36231055, 2022).
neurodegenerative disease (continued). "Whether age-dependent loss of TAK1 and, based on the findings of our study, presumably, a decrease of the TAK1-IKKα/β-Hsc70 signaling that would result in a decrease of CMA-mediated clearance of APP contributes to the pathogenesis of AD or other neurodegenerative diseases remains to be investigated." (PMID 34291435, 2021). "However, based on the present study and in vitro model, picein could be used in transgenic APP/PS1 mice (AD animal model) for the treatment of neurodegenerative diseases for future research." (PMID 32630418, 2020). "However, its over-activation may lead to the genesis and cleavage of APP (amyloid-beta precursor protein), which has been recognized as a key biomarker for the progression of neurodegenerative diseases like AD." (PMID 32630418, 2020). "Furthermore, these changes in protein trafficking may be extended to other biomarkers related to neurodegenerative diseases, such as PrPc, APP and glutamatergic receptors." (PMID 31068782, 2019). "The increase in the number of proliferating neuroblasts is not limited to the prodromal stages of AD pathology but is also seen in other neurodegenerative diseases suggesting that other non-APP specific factors might contribute to modulation of neurogenesis in neurodegeneration." (PMID 27544234, 2016). "Further studies on the role of APP in the pathogenesis of AD and other neurodegenerative diseases using our new cellular model for intracellular tau accumulation in cells expressing APP may lead to the development of new therapies and pharmaceuticals for these diseases." (PMID 25869641, 2015). "In neurodegenerative diseases, ITM2B and its truncations play distinct roles in processing amyloid‐beta precursor (APP)." (PMID 41319268, 2026). "First, the exclusive use of male APP/PS1 mice introduces potential sex-specific biases, as estrogen has been shown to modulate both vagal tone and neuroinflammation in neurodegenerative diseases." (PMID 41233833, 2025). "Further clinical studies should evaluate the mutations of APP and its mediated pathways or molecules in both PDR and AD patients, and this could be implemented in PDR screening programs to reduce the risk of developing progressive neurodegenerative diseases like AD." (PMID 38328307, 2023). "In summary, both APP and SPI1 are related to protein homeostasis and even accelerate the development of both T2DM and neurodegenerative diseases (NDs)." (PMID 37293508, 2023). "In particular, Pin1 regulates several neuronal proteins, such as Tau, amyloid precursor protein (APP), and α-synuclein and thus has a significant impact on the development of many neurodegenerative diseases." (PMID 36304997, 2022). "In many studies, it was proven to be effective in the treatment of neurodegenerative diseases since the increase of ADAM10 activity, which was the main α-secretase, which broke the APP, protected the brain from the accumulation of Aβ in AD." (PMID 35957121, 2022). "Plaque size and number in APP/PS1 mice continued to increase with age, suggesting very early neuronal damage and an important role for early intervention to alleviate neurodegenerative disease." (PMID 35356237, 2022). "Inhibition of Drp1 ameliorates mitochondrial and synaptic dysfunction in 7 month-old APP/PS1 and 3 month-old CRND8 APP transgenic AD mice, as well as in other neurodegenerative diseases." (PMID 34955809, 2021). "Although emerging evidence has shown that Pin1 directly or indirectly regulates neuronal proteins such as Tau, amyloid precursor protein (APP), and α-synuclein, the physiological functions of Pin1 in neurodegenerative diseases remain to be elucidated." (PMID 33537091, 2021). "The involvement of APP and MAPT in certain neurodegenerative diseases, ageing, and most importantly, in TBI is well documented and supportive of our findings." (PMID 34572074, 2021).
neurodegenerative disease (continued). "The topological analysis suggests that the amyloid-beta precursor protein (APP) was the major neighboring protein of BACE1, and its potential role in the pathogenies of neurodegenerative diseases has also been reported." (PMID 32630418, 2020). "Numerous proteins were specifically secreted from only one cell type, such as APP from neurons or granulin (GRN) from microglia, which have major roles in neurodegenerative diseases." (PMID 32954517, 2020). "Similar to APP/MAPT transgenic mice, most other neurodegenerative disease mouse models strongly activated expression signatures overlapping with the cluster B and cluster C modules from human brain." (PMID 32668255, 2020). "The gene expression of amyloid precursor protein (APP), a biomarker of neurodegenerative disease, was affected by particle exposure." (PMID 30654492, 2019). "To further extend its therapeutic activities for human neurodegenerative diseases, herein, we investigated the effect of URMC-099 in APP/PS1 double-transgenic mice, a widely used AD animal model." (PMID 29729668, 2018). "The identification of DJ-1 and amyloid beta precursor protein AP4 in the thiazolium proteome may be linked to the antioxidant cluster of the thiamin and thiazolium proteomes, supporting the thiamin significance in neurodegenerative diseases beyond the NAD(P)H production by ThDP-dependent enzymes." (PMID 26212886, 2015). "Detailed biochemical and genetic studies about APP, MAPT and PTEN molecular processing will be crucial to the development of therapeutic targets to treat many neurodegenerative diseases." (PMID 24688734, 2013). "It remains uncertain whether and how BACE1 is associated with aging or neurodegenerative disease since under our experimental conditions BACE1 mRNA levels significantly decreased during physiological aging and beside the increase in the expression of APP, they remain unchanged in AD-PBMCs." (PMID 22414021, 2012). "P-TAU and APP have demonstrated specificity to AD versus non-AD neurodegenerative diseases, which were critical for clinical diagnosis and eligibility for therapies." (PMID 41164084, 2025). "Since neurodegenerative diseases, such as AD, PD, FTD, PSP and ALS, share a similar genetic basis and SNPs of APP were reported to be involved in AD progression, we investigated the effect of SNPs of APP in sALS patients." (PMID 36707813, 2023). "In relation to these data, the elimination of APP expression should not be taken as a potential therapy for certain neurodegenerative diseases (such as AD)." (PMID 37834082, 2023). "APP/BIN1/COPS5 3xTg-AD mice are a suitable model for evaluating epigenetic changes in AD, the discovery of new epigenetic-related biomarkers for AD diagnosis, and new epidrugs for the treatment of this neurodegenerative disease." (PMID 35269588, 2022). "Moreover, AEPs process phosphatase 2A inhibitor SET, tau protein and amyloid precursor protein (APP) in neurons; therefore, they may play a vital role in the onset and progression of neurodegenerative diseases." (PMID 36142134, 2022). "Overall, these evidences suggest that NGF-based therapy could improve neurological outcomes that are related to dysfunctions of the central cholinergic system, both in neurodegenerative diseases and after TBI, normalizing APP and tau metabolism in TrkA-expressing cells." (PMID 34867367, 2021). "Moreover, astrocytes express amyloid precursor protein (APP), a biomarker of neurodegenerative disease, which after proteolytic processing gives rise to Amyloid β that may accumulate in the extracellular space." (PMID 30654492, 2019).
neurodegenerative disease (continued). "Additionally, further APP fragments were discovered and TDP-43 as well as β-glucocerebrosidase and ERK 1/2 were proposed as potential novel candidate biomarkers for the early and differential diagnosis of neurodegenerative diseases." (PMID 20886057, 2010).
cancer (173 papers, 2011 to 2026). A tumor composed of atypical neoplastic, often pleomorphic cells that invade other tissues. "The link between the growth-promoting effects of androgens and the associated increase in APP provides impetus to understand the androgenic regulation of APP processing pathways and its potential implications for cancer." (PMID 41614805, 2025). "Due to its role in inflammation and cell proliferation, amyloid-beta precursor protein has been implicated in several malignant cancers including GBM." (PMID 38613388, 2024). "This device was used to develop models of CNS disorders, bacterial infections, cancer, or edema, by introducing Aβ (adding cells expressing APP variants), bacterial conditioned media or bacterial toxin, cancer cells, or ammonium chloride, respectively." (PMID 38263227, 2024). "APP dysregulation is associated with various cancer processes, including cell proliferation, migration, invasion, and chemoresistance." (PMID 39332525, 2024). "Although APP is positively associated with androgen receptor, a recent study reported a marginal association between APP and AR expression in luminal A cancer." (PMID 34066808, 2021). "Counterintuitively, increased levels of APP have been found in a number of cancers, with worse outcomes associated with higher APP levels." (PMID 32728795, 2020). "CCL22 correlates with a systemic inflammation response index that predicts survival of patients with PDAC, and APP has been linked to tumor growth in experimental cancers, including PDAC." (PMID 33334063, 2020). "Major functional components of this network (TNF, MAPK, TRIM21 and APP) were associated with metabolism and cancer." (PMID 32228434, 2020). "Overexpression of APP, particularly the soluble N-terminal ectodomain (sAPP), has been linked to carcinogenesis, including cancers originating from the nasopharynx, oral cavity, lung, breast, thyroid, parathyroid, colon, testicles, and pancreas." (PMID 25926793, 2015). "We performed in silico mutational analysis in order to observe the effect of the mutations on the A2M - APP interaction, and found a possible association between abrogation of this interaction and cancer." (PMID 25056661, 2014). "APP has a well-established role in Alzheimer’s disease, as evidenced by epidemiological studies demonstrating an inverse association between Alzheimer’s disease and cancer incidence and prevalence." (PMID 39332525, 2024). "Recent studies have demonstrated the association of APP and Aβ with cancer, suggesting that BACE1 may play an important role in carcinogenesis." (PMID 38201438, 2023). "Several genes [e.g., epidermal growth factor receptor (EGFR) and amyloid precursor protein (APP)] are associated with both cancer and AD, and we and others have recently found that anti-cancer drugs can penetrate the blood-brain barrier (BBB) and modulate AD pathology." (PMID 37601068, 2023). "ADM-2 is an ortholog of the human ADAM9, which is implicated in inflammation, cancer, and AD by cleaving the APP, but whether ADAM9 plays a potential role in Aβ removal is unknown." (PMID 37728486, 2023). "A miss regulation could lead to the presence of the most abundant APP-mRNA isoform that would be a defective one encoding consequently a defective APP protein isoform (or its proteolytic fragments) capable of promoting cancer growth." (PMID 34877405, 2021). "Mutations that destabilize this interaction may prevent or reduce the degradation of Ab by LRP and cause a rise in APP level, which may eventually lead to increased cancer cellular proliferation." (PMID 25056661, 2014). "APP's function as a mitogenic molecule is evident from the fact that its upregulation is associated with cancers of different organs; neurons being postmitotic are fully differentiated and undergo apoptosis rather than transformation upon cell cycle activation." (PMID 22112898, 2011).
cancer (continued). "Lastly and perhaps related to the growth promoting property of APP, an area that has come to light concerning APP function involves carcinogenesis, coinciding with the recent observation of an inverse association between cancer and AD." (PMID 21527012, 2011). "These expressions vectors, with or without GPI anchor, could be used as tools for (a) studying the effects of Arg393His mutation in AT; (b) studying the emerging role of Arg393His mutation in AT and cancer; (c) studying intermolecular interactions between APP and AT." (PMID 35860682, 2022). "APP may be associated with a more aggressive cancer in TGCTs." (PMID 23662100, 2013). "Using short hairpin RNA (shRNA)-mediated protein knockdown, we generated cancer cell lines with significantly reduced APP expression." (PMID 42246097, 2026). "This systematic review was conducted through a comprehensive search of PubMed, Scopus, Web of Science, and EMBASE between 2000 to 2024 for studies examining the effects of androgens on APP and its cleavage enzymes in cancer." (PMID 41614805, 2025). "Across all methods, we observed convergence on FCGR2A and APP as key targets, supporting their robust involvement in cancer–platelet signaling." (PMID 41226816, 2025). "Taken together, our integrative strategy revealed ITGA2B, FLNA, GRB2, FCGR2A, and APP as high-confidence, FDA-targetable candidates that intersect cancer-associated platelet education with pro-metastatic platelet signaling." (PMID 41226816, 2025). "Consistent with these functions, APP has been reported to be overexpressed in various cancers, including glioblastoma, breast, prostate, pancreatic, lung, and colon cancers." (PMID 41614805, 2025). "There are likely many reasons why little has been published regarding the impact of androgen on APP processing pathways in cancer." (PMID 41614805, 2025). "Further studies are needed to explore the interaction between androgens and APP processing in other cancer types, as well as to elucidate downstream signaling pathways regulated at the gene expression level." (PMID 41614805, 2025). "This is the first systematic review to investigate the literature on the impact of androgens on APP and its cleavage enzymes in relation to cancer." (PMID 41614805, 2025). "Recent research has shed light on the diverse roles of APP in cancer, particularly in signalling pathways." (PMID 38445803, 2024). "A product generated during APP processing, sAPPα, has been revealed to play an important role in several cancer progressions." (PMID 39332525, 2024). "Overexpression of APP in cancer cells promotes cell proliferation and migration, reduces apoptosis, decreases treatment sensitivity, and impairs survival rates, which matches our rescue experiment." (PMID 39332525, 2024). "We found that each subtype of secretase primarily cleaves APP and Notch as substrates, regulating Aβ levels through APP cleavage to impact the progression of AD, while also cleaving Notch receptors to affect cancer progression." (PMID 39634655, 2024). "This article elaborates on the secretases with APP and Notch as the main cleavage substrates, indicating that different subtypes of secretases play a crucial role in AD and cancer progression." (PMID 39634655, 2024). "CD74 was significantly upregulated in cancer cells in GGN and was strongly associated with APP and COPA in alveolar epithelial cells, ciliated cells, and endothelial cells." (PMID 37745301, 2023). "In cancer and neurodegeneration, APP, Cyclin D, and Cyclin E are up-regulated, whereas PTPA is down-regulated." (PMID 37383425, 2023). "Present study has unavoidable limitation of using four genes APP, CCND1, CCNE1, and PTPA only, since so far only four genes have been identified those are commonly implicated in cancer and neurodegeneration." (PMID 37383425, 2023). "Laminin, MHC-I, APP, MK, and annexin are significantly involved in cellular interaction and communication for cancer cells and immune cells." (PMID 36835933, 2023).